YY1 (YY1 transcription factor)
Diseases named in the same sentence as YY1 in open-access papers (continued):
Sharing a sentence is not in itself a finding about the gene and the disease.
tumor (continued). "Thus, regulation of PSCA by YY1 is likely to be context-dependent and modulated during tumor progression." (PMID 22536409, 2012). "Although the correlation between YY1 expression and prognosis may merely be a statistical association, the protein dosage points to a functional relationship between YY1 overexpression and a more aggressive tumor phenotype." (PMID 22047406, 2011). "The prediction of mesenchymal transcription factor activity (MYOD1 and YY1) could be indicative of an epithelial-mesenchymal transition, which has lately been related to tumor progenitor cell plasticity." (PMID 20500816, 2010). "In the current study, we used a large (n = 1,176) and well characterised series of patients with early stage invasive breast cancer to investigate the frequency of discordant HER2 gene and protein levels and to evaluate the role of AP-2α/β, AP-2α and YY1 in these tumours." (PMID 20025767, 2009). "The AP-2 and YY1 antibodies were tested using Kaplan Meier plots to model clinical outcome, and using Cox regression analysis to determine their ability to predict clinical outcome measured against tumour size, grade, and lymph node stage." (PMID 20025767, 2009). "This suggests that YY1 may contribute to tumor progression and metastasis." (PMID 40088083, 2025). "Furthermore, YY1 can rewire tumor cell metabolism by upregulating glycolytic enzymes and glutamine transporters and enhance tumor cells’ metastatic potential by reshaping the tumor microenvironment." (PMID 40867514, 2025). "In addition, YY1 facilitates tumor progression by regulating tumor immune response." (PMID 40867514, 2025). "In summary, our findings highlight for the first time nuclear YY1 expression as a promising independent prognostic biomarker in BC, particularly in underrepresented populations, such as Latin American patients, when quantified using DP and a tumor-focused TMA analysis." (PMID 41009346, 2025). "Moreover, preclinical models have shown that genetic or pharmacological inhibition of YY1 sensitizes resistant tumor cells to conventional treatments, highlighting its potential as a biomarker for predicting therapy and a treatment target for overcoming drug resistance." (PMID 40867514, 2025). "Moreover, while YY1 is generally considered oncogenic, it may exhibit tumor-suppressive functions in certain cancer types, necessitating evaluation in a context-dependent manner." (PMID 38893192, 2024). "Therefore, the role of YY1 in tumor immune resistance may be related to the overexpression of PD-L1 on cancer cells and plausibly LAG-3 on CD8 T cells." (PMID 39796650, 2024). "Therefore, the activation of TRIAP1 and suppression of LC3B might contribute to the tumor-promoting function of YY1 in CRC." (PMID 38769122, 2024). "Thus, the YY1-mediated activation of MMP expression facilitates the invasion of tumor cells." (PMID 38893192, 2024). "Moreover, the potential to develop resistance to YY1 inhibitors during the treatment process poses a substantial challenge, as tumor cells may adjust and develop strategies to counteract the inhibitory effects of these drugs, diminishing their efficacies." (PMID 38893192, 2024). "In addition, Silibinin reduces GBM tumor growth by regulating YY1/SLC1A5 pathway." (PMID 38410123, 2024). "Thus, the role of YY1 in the further enhancement of PD-1 and/or PD-L1 expression may further contribute to the suppression of the anti-tumor immune response, allowing GBM cells to grow and metastasize." (PMID 38893192, 2024). "Combining a YY1 inhibitor with an immunotherapy agent that targets the immune system’s response to tumors could enhance the immune system’s ability to recognize and destroy tumor cells, potentially improving patient survival." (PMID 39796650, 2024). "YY1 may promote tumor angiogenesis in a HIF-1-independent manner via the DEK oncogene." (PMID 38339244, 2024).
tumor (continued). "Moreover, YY1 used in combination with various immunotherapy approaches may provide an enhanced anti-tumor effect via downregulation of certain immune players, such as PD-L1." (PMID 38893192, 2024). "Notably, in addition to the beneficial effects of targeting YY1 in CD8 T cells to inhibit the expression of inhibitory receptors, we also suggest targeting YY1 overexpressed in the tumor cells, which will also inhibit PD-L1 expression and other YY1-associated pro-tumorigenic activities." (PMID 39796650, 2024). "Galiximab, a chimeric monoclonal antibody that targets CD80 and is currently in phase II clinical trials for the treatment of follicular lymphoma, could also downregulate YY1 expression by inhibiting NF-κB, which resulted in the induction of apoptosis in tumor cells." (PMID 37444616, 2023). "Furthermore, YY1 also promotes tumor angiogenesis by activating the transcription of VEGF while suppressing anti-angiogenic factors such as thrombospondin-1 (TSP-1), pigment epithelium-derived factor (PEDF), and tissue inhibitor of metalloproteinase 2 (TIMP-2)." (PMID 37444616, 2023). "The expression of YY1/nuclear factor‐κ‐gene binding P65 (NF‐кB‐P65) complex indirectly regulated by Lnc‐TLCD2‐1 may negatively mediate the radio‐sensitivity of CRC cell lines by regulating tumor microenvironment infiltration of immune cells." (PMID 36880159, 2023). "However, the role of YY1 in promoting or suppressing tumor growth and spread remains controversial and apparently conflicting, as different and still unclear molecular mechanisms of YY1 action may exist in a cancer-type specific context." (PMID 37894300, 2023). "The role of YY1 in the promotion or suppression of tumor growth remains controversial and its regulatory effects may depend upon not only cancer types, but also its interacting partners, chromatin structure, and the context in which it acts at least in experimental settings." (PMID 36880159, 2023). "In contrast, in a considerable number of tumors, YY1 expression was negatively associated with intra-tumoral abundance of CD8 T cells, follicular T helper cells (Tfh), as well as with memory B cells, which are all known to promote the formation of an immunoreactive tumor microenvironment." (PMID 37894300, 2023). "Thus, determining the stable factor of YY1 may be an effective way to reduce YY1 levels in tumor cells." (PMID 37408047, 2023). "In addition, some studies have suggested that YY1 inhibition may sensitize tumor cells to other therapies, such as radiation and immunotherapy." (PMID 37444616, 2023). "Therefore, nitric oxide donors such as DETA-NONOate have great potential as antitumor therapy that targets YY1 and can enhance the cytotoxicity of antitumor therapies that depend on Fas-induced apoptotic tumor cell death, such as cell-mediated immunotherapy and immune checkpoint inhibition." (PMID 37444616, 2023). "For example, combining a YY1 inhibitor with an immunotherapy agent that targets the immune system’s response to tumors could enhance the immune system’s ability to recognize and destroy tumor cells, potentially improving patient survival." (PMID 37444616, 2023). "In addition, a xenograft model in immunodeficient mice showed that tumors derived from MHCC-97H cells with decreased GRSF1 expression resulted in smaller tumor sizes (sh-GRSF1 group) and that YY1 overexpression (sh-GRSF1+ov-YY1 group) promoted tumor growth (p<0.05)." (PMID 34998399, 2022). "Therefore, combined treatment with YY1 inhibitors may help overcome the problem of tumor cells’ resistance." (PMID 35719931, 2022). "Several studies have reported that YY1 could promote the tumor progression of CRC." (PMID 36003333, 2022).
tumor (continued). "Therefore, YY1 inhibition could be considered as a potential tumor therapeutic strategy to give consistent clinical outcomesYY1 is associated with HIF-1 α regulation under hypoxia, and targeting YY1 might be a potential therapeutic strategy of solid cancer." (PMID 35163649, 2022). "In many cancer types, the expression of YY1 in tumors was considerably greater than in normal tissues, indicating that YY1 may play a part in tumor incidence and progression, whereas whether YY1 plays a part in the occurrence and development of many cancers via common molecular pathways is unknown." (PMID 35791393, 2022). "In addition, YY1 may affect the level of immune cell infiltration and promote tumor cell immune escape." (PMID 35359580, 2022). "In addition, YY1 also has the effect of inhibiting tumor progression in LC." (PMID 33758616, 2021). "Therefore, we hypothesized that miR-7 can play a role as tumor suppressor, through negative regulation of YY1 and KLF4 expression, affecting the cell migration and chemoresistance in NHL." (PMID 33194748, 2020). "Therefore, the role of YY1 in tumor immune resistance may be related to the overexpression of PD-L1 on cancer cells." (PMID 33344447, 2020). "Therefore, elevated YY1 expression in tumor cells might represent a hurdle during tumor treatment with DNA-damaging drugs." (PMID 32226547, 2020). "Furthermore, YY1 might positively regulate the expression of programmed death ligand 1 (PD-L1), whose expression is correlated with poor clinical response to cell-mediated anti-tumor therapy, through crosstalk between YY1 and PD-L1 signaling pathways 119-121." (PMID 32226547, 2020). "Functionally, YY1 could silence tumor-suppressive miRNAs in HCC." (PMID 32272940, 2020). "However, it needs to be examined whether these drugs could be applied to specifically target YY1 in ECs and tumor angiogenesis." (PMID 33235311, 2020). "O-GlcNAcylation and YY1 may therefore be important co-ordinators of tumour progression and immune suppression, driven by alterations in metabolism and the melatonergic pathway in cells of the tumour microenvironment." (PMID 33375613, 2020). "However, the relationship between YY1 and endothelial cell-dependent tumor angiogenesis in HCC remains unclear." (PMID 31799179, 2019). "Thus, by blocking CDKN3 expression YY1 promotes p21 expression and tumor suppression." (PMID 31824839, 2019). "Because YY1 inhibition by NO leads to the sensitization of cancer cells to both chemotherapy and immunotherapy, and YY1 mediates the expression of PD-L1 in tumor cells, NO may play a role in sensitizing tumor cells to anti-PD1/anti-PD-L1 therapy." (PMID 31533363, 2019). "Hence, YY1 might also regulate lipid metabolism-related factors at their transcriptional level, indicating that although further investigation is needed, there might be alternative pathways of YY1 regulation on tumor cells lipid metabolism." (PMID 31695789, 2019). "The expression of YY1 in CSCC tissues was positively correlated with advance FIGO stage, but was not correlated with the tumor differentiation, suggesting that YY1 may also be associated the CSCC infiltration." (PMID 29470526, 2018). "On the other hand, YY1 might exert tumor suppressive functions in certain types of cancers." (PMID 28827574, 2017). "Similar to MYCT1, YY1 may act as an oncogene or a tumor suppressor in different cancer types." (PMID 28485541, 2017). "In addition, The Yin-Yang 1 protein (YY1), a ubiquitously expressed zinc-finger transcription factor, accumulates in the nucleus during ‘S’ phase and nuclear export of YY1 is shown to be critical for the inhibition of cellular transformation and tumor growth." (PMID 26274615, 2015). "The findings demonstrating PDT-induced NO on the dysregulated NF-κB/Snail/YY1//RKIP loop suggested that inhibitors of NF-κB/Snail/YY1 or inducers of RKIP may be useful if used in combination with PDT for anti-tumor cell activity, and such studies are currently being explored." (PMID 26319434, 2015).
tumor (continued). "In contrast, YY1 might serve as a tumor suppressor gene in several cancer types." (PMID 24674326, 2014). "The present study suggested that YY1 plays a negative role, i.e. is a tumor suppressor, in PDAC, and may become a valuable diagnostic and prognostic marker of PDAC." (PMID 24884523, 2014). "While a role for RelA and YY1 in the repression of Bim in MM is highly novel, it will be interesting to study whether the YY1-RelA complex is frequently formed in other types of cancers to repress Bim and promote tumor cell survival." (PMID 23874387, 2013). "To this end, we first analyzed whether YY1 is hyperexpressed in primary MM tumor cells." (PMID 23874387, 2013). "Similarly, changes in YY1 levels together with changes in systemic androgen may modulate PSCA expression during tumor progression." (PMID 22536409, 2012). "Then, we identified YY1 as a critical upstream transcription factor that bound to the promoter of CARD9 and repressed it, accompanied with DC dysfunction and tumor growth." (PMID 42212326, 2026). "Through the regulation of the SENP1/METTL3/MYC axis, YY1 promotes the self-renewal of GBM cells contributing to the maintenance of cancer cell population, promoting tumor growth and contributing to the progression of the disease." (PMID 39904836, 2025). "The lactylation of CENPA at the K124 site promotes CENPA activation and cooperates with Yin Yang-1 (YY1) to drive cyclin D1 and neuropilin two expressions, which in turn promotes tumor growth." (PMID 40584617, 2025). "Yin Yang 1 (YY1) is a critical oncogene overexpressed in many tumors and mediates multiple tumor-related processes, such as cell proliferation, metabolic reprogramming, immune evasion, and drug resistance." (PMID 40867514, 2025). "Knockdown of MAGEA6 significantly reduced CRC cell migration, invasion, and PNI both in vitro and in vivo; 3) MAGEA6 promotes YY1 deubiquitination, enhancing CXCL1 expression and SC recruitment, while also driving tumor cell EMT." (PMID 40145793, 2025). "Downregulation of YY1 subsequently reduced the expression of HER2 and its downstream kinases further inhibiting tumor progression." (PMID 41327312, 2025). "Upon YY1 inhibition and subsequent decreased expression of PFKP, there was a decrease in tumor cell proliferation and enhanced apoptosis." (PMID 41327312, 2025). "An important pathway involving YY1 is the NF-κB/YY1/ RKIP regulatory axis, which has been shown to significantly contribute to tumor cell resistance against both chemotherapy and immunotherapy-induced cytotoxicity." (PMID 40867514, 2025). "Prior research has established that in BCa, H3K18la promotes tumor proliferation and migration by up-regulating LCN2 expression, and facilitates cisplatin resistance by enhancing the expression of YBX1 and YY1." (PMID 41199784, 2025). "YY1 acts as a downstream effector in the NF-κB/SNAIL pathway, repressing RKIP expression to promote tumor EMT and treatment resistance, while NO donors downregulate YY1 to restore RKIP activity and reverse drug resistance." (PMID 40867514, 2025). "The overexpression of YY1, a multifunctional transcription factor, correlates with downregulation of RKIP, a well-established tumor suppressor." (PMID 41327312, 2025). "Using a Cox proportional hazards model, they further showed that YY1 overexpression was an independent prognostic factor by adjusting for hormone receptor/HER2 status and tumor size." (PMID 41009346, 2025). "We analysed the correlation between YY1 and USP18 expression in 33 cancer tissues from the TCGA and observed a positive correlation between YY1 and USP18 across various tumour types." (PMID 40374599, 2025). "When YY1 expression is high, MZF1 is transactivated, leading to enhanced glucose uptake, lactate production, ATP generation, and increased tumor cell viability and invasiveness." (PMID 41327312, 2025).
tumor (continued). "According to the UALCAN database, the expression levels of PVT1, hsa-miR-143–3p, CDK1, FOXC1, YY1, and GATA2 show statistically significant differences between primary tumor samples and normal samples in the TCGA-LUAD dataset." (PMID 41080754, 2025). "YY1 suppressed GALC gene transcription, consequently increasing galactosyl cerebroside accumulation and enhancing tumor cells’ resistance to doxorubicin." (PMID 40867514, 2025). "YY1 and RKIP both modulate immune and inflammatory processes within the tumor microenvironment, but do so in opposing manners." (PMID 41327312, 2025). "YY1, a transcription factor, is overexpressed in CRC and promotes tumor growth, metastasis and drug resistance." (PMID 38351178, 2024). "In Hepatocellular carcinoma, YY1 positively up-regulates EGFR, which enhances tumor cell proliferation and sorafenib resistance." (PMID 38351178, 2024). "The MAPK pathway activates YY1 expression, and its inhibition by MEK inhibitors leads to inhibiting both PD-1 and YY1 expressions and showing stronger anti-tumor effects than seen with just the PD-1 antibody." (PMID 39796650, 2024). "YY1 is an important regulator of the EMT and migration of HCC cells, and, thus, can be targeted to inhibit HCC tumor growth through ISO." (PMID 38539569, 2024). "RKIP upregulation in tumor cells also resulted in the upregulation of Fas and DR5 via the RKIP-mediated inhibition of NF-κB and YY1." (PMID 39796650, 2024). "In addition, while existing checkpoint inhibitors focus on immune cells, YY1′s role in tumor cells—regulating PD-L1 expression, proliferation, metastasis, and resistance—provides an opportunity for dual-action therapies that target both tumor progression and immune escape mechanisms." (PMID 39796650, 2024). "The authors conclude by underscoring YY1’s role as an oncogene and its potential as a therapeutic target to inhibit EMT and halt tumor progression." (PMID 38893192, 2024). "We report the regulation of PD-L1 by YY1 at the transcriptional, post-transcriptional, and post-translational levels, resulting in the restoration of CD8+ T cells’ anti-tumor functions." (PMID 38539569, 2024). "The observed correlations between YY1/LAG-3 expression and immune infiltration highlight their significant role in modulating the tumor microenvironment." (PMID 39796650, 2024). "IHC score indicated that PRR11, KIF11, RACGAP1, YY1, CREB1 expression was significantly increased in HCC tissues compared to adjacent para-tumor tissues." (PMID 39530087, 2024). "This review systematically explores the diverse roles of YY1 overexpression and activities in GBM, including its impact on the tumor microenvironment (TME) and immune evasion mechanisms." (PMID 38893192, 2024). "Immunohistochemical staining and Western blotting were used to observe the expression of risk model factors PRR11, KIF11, RACGAP1 as well as the potential common transcription factors YY1, CREB1 and SUZ12 in HCC tissues and para-tumor tissues." (PMID 39530087, 2024). "Through analysis, we confirm that YY1 expression is related to the WHO grade and tumor size of GBM patients." (PMID 38410123, 2024). "USP21 is known to deubiquitinate and stabilize several transcription factors such as YY1, FOXM1, EZH2, Nanog, and GATA3, promoting cancer cell proliferation, migration, and invasion and in vivo tumor growth." (PMID 39305962, 2024). "NF-κB plays a crucial role in tumor proliferation and resistance development, and has been reported to regulate the transcriptional expression of HIF-1α and YY1 transcription factors." (PMID 39063014, 2024). "PLA results on tumor tissue illustrated that the supplementation of VD3 promotes the interaction between YY1 and VDR at the tumor site, with a significant increase also observed in the interaction between VDBP and Twist1." (PMID 38164156, 2024).